NTS (neurotensin)
Diseases named in the same sentence as NTS in open-access papers (continued):
Sharing a sentence is not in itself a finding about the gene and the disease.
colitis (1 paper, 2021). Inflammation of the colon. "We focused on β-endorphin, vasoactive intestinal peptide (VIP), neurotensin, enkephalins, substance P and bradykinin because these peptides are linked to pain sensitization or inflammation and, as such, are relevant in the pathophysiology of colitis." (PMID 34639054, 2021). "There was a significant decrease of the full-length neurotensin only after 20 min of incubation with acute colitis samples (p = 0.02), indicating a rather slow process." (PMID 34639054, 2021). "Treatment with neurotensin after colitis induction reduced mucosal damage, suggesting a role for neurotensin in mucosal healing following colitis." (PMID 34639054, 2021). "Our results suggest very rapid cleavage of neurotensin by proteases in control samples but only slow cleavage by proteases in acute and post-colitis samples." (PMID 34639054, 2021).
colon adenocarcinoma (1 paper, 2022). "However, the cited experiments included the exposure of neurotensin to dog ileum and to cell cultures including human colon adenocarcinoma cells and might therefore not apply to samples measured in human serum." (PMID 35345492, 2022).
Colorectal Polyp and (1 paper, 2019). "We conducted a large-scale prospective study to further investigate the diagnostic potential of plasma neurotensin as a diagnostic marker for colorectal polyps and cancers in patients who have symptoms which fulfil UK national criteria for suspected colorectal cancer." (PMID 31093954, 2019).
colorectal tumors (1 paper, 2015). "Among these, we focused on neurotensin receptor 1 (NTSR1) because although neurotensin (NTS) signaling has been strongly implicated in tumorigenesis, methylation of NTSR1 has not yet been reported in colorectal tumors." (PMID 26334593, 2015).
Constipation (1 paper, 2019). Infrequent or difficult evacuation of feces. "A recent study reported that some GI peptides, particularly neurotensin and motilin, are linked to impaired colonic motility in STC constipation." (PMID 31737065, 2019).
eating disorder (1 paper, 2021). A broad group of psychological disorders with abnormal eating behaviors leading to physiological effects from overeating or insufficient food intake. "Only in obese women neurotensin and xenin showed positive correlations with depressiveness and eating disorder symptoms." (PMID 33664656, 2021).
endometrial cancer (1 paper, 2024). Primary or metastatic malignant neoplasm involving the endometrium (mucous membrane that lines the endometrial cavity). "The research on neurotensin in endometrial cancer is limited." (PMID 39334861, 2024).
fibromyalgia (1 paper, 2015). A chronic disorder of unknown etiology characterized by pain, stiffness, and tenderness in the muscles of neck, shoulders, back, hips, arms, and legs. "It has been theorized that it plays a part in fibromyalgia and showed prokinetic properties, whilst was found to secrete serotonin as well as substance P and neurotensin by intestinal protozoa." (PMID 25815090, 2015).
Headache (1 paper, 2024). Cephalgia, or pain sensed in various parts of the head, not confined to the area of distribution of any nerve. "Interestingly, Nts, neurotensin, was overlapped in the majority of the injury or headache model, and it has been well documented that neurotensin modulate neuropathic pain." (PMID 39578726, 2024).
inflammatory skin disease (1 paper, 2014). Inflammatory skin disorders covers a broad category that includes many conditions ranging in severity, from mild itching to grave medical health complications These disorders are common in people of all ages and races. "Overall our results suggest that neurotensin may be of great value in therapeutic approaches for inflammatory skin diseases, through promoting wound healing." (PMID 25180119, 2014).
liver cancer (1 paper, 2012). An epithelial or non-epithelial malignant neoplasm that arises from the liver. "In one study on neurotensin, 20 patients with liver cancer were studied for serum neurotensin levels: five patients had elevated levels and four were diagnosed with FLC." (PMID 24278737, 2012).
liver fibrosis (1 paper, 2014). "It is thus, plausible that gastric neurotensin enters the liver via the portal vein and alleviates liver fibrosis." (PMID 24716593, 2014).
lung diseases (1 paper, 2021). "Mounting evidence indicates that the expression of NTs and their homologous receptors in the NT signaling pathways is changed in lung diseases." (PMID 34306156, 2021).
medulloblastoma (1 paper, 2017). A malignant, invasive embryonal neoplasm arising from the cerebellum. "Neurotensin (NT) is a 13 amino acids peptide (pEYENKPRRPYIL) targeting three different receptors (NTR1, NTR2, NTR3) over expressed in different human cancers including Ewing Sarcomas, meningiomas, astrocytomas, medulloblastomas and pancreatic carcinomas." (PMID 28767081, 2017).
pheochromocytoma (1 paper, 2017). "Thirty patients had tumor markers within 30 days of starting treatment and periodically while on treatment (pancreastatin, gastrin, glucagon, neurotensin; metenephrines for pheochromocytoma/paraganlgioma)." (PMID 29262620, 2017).
psychosis (1 paper, 2023). "Research evidence has already identified the role of neurotensin in the pathophysiology of psychosis and the mechanism of action of antipsychotic drugs." (PMID 37275985, 2023).
small lung cell carcinoma (1 paper, 1984). "The results suggest that small lung cell carcinoma lines may be useful for studying the biosynthesis of human neurotensin." (PMID 6087865, 1984).
Stroke (1 paper, 2021). Sudden impairment of blood flow to a part of the brain due to occlusion or rupture of an artery to the brain. "Furthermore, findings of several clinical studies support these preclinical observations by documenting that the severity of stroke and traumatic brain injury, and subsequent mortality, is associated with elevated levels of bradykinin, substance P, and neurotensin." (PMID 33687143, 2021). "Experimental studies have documented altered expression of Nln in several disease conditions including stroke, and suggested its cerebroprotective function via inactivation of bradykinin, substance P, and neurotensin, and formation of angiotensin‐(1‐7) and enkephalins." (PMID 33687143, 2021).
tongue cancer (1 paper, 2025). A malignant neoplasm affecting the tongue. "The findings revealed that, in comparison to their levels in normal tissues, the genes GAL, GHRH, LCE2B, PCDHGC5, and MT3 were notably upregulated in tongue cancer, while NTS was downregulated." (PMID 40255484, 2025).
trypanosomiasis (1 paper, 2021). Infection with protozoa of the genus trypanosoma. "Additional genes highlighted in our study were CFH, TRNT1, IL5RA, MGAT4C and NTS, which could be also relevant for the trypanosomiasis resistance in cattle." (PMID 34351956, 2021).
ulcerations (1 paper, 2012). "Considering a wide variety of effects mediated by neurotensinergic system, neurotensin may represent a potential therapeutic target in disorders associated with chronic mucosal ulcerations." (PMID 23492756, 2012).
cancer (43 papers, 2010 to 2025). A tumor composed of atypical neoplastic, often pleomorphic cells that invade other tissues. "Identifying the role of Neurotensin in the underlying molecular mechanisms in various cancers can give way to developing new agnostic drugs and personalizing treatment according to the genomic structure of various cancers." (PMID 32336282, 2020). "FFAs have also been demonstrated to regulate expression and secretion of hormones and neuropeptides, including the gastrointestinal neuropeptide neurotensin (NT), which is implicated in the promotion of obesity and the development of several types of cancer." (PMID 30917119, 2019). "Natural neurotensin is rapidly degraded in the blood by endogenous peptidases, thus several modified analogues have been developed for diagnostic imaging in cancer." (PMID 28767081, 2017). "Neurotensin has also been implicated in the progression of cancers of the pancreas, breast, lung, and prostate." (PMID 21961726, 2011). "Many cancers, including pancreatic, colorectal, prostate, breast, and lung cancers and glioma, overexpress neurotensin and/or its receptor." (PMID 41301028, 2025). "Neurotensin acts as a growth-promoting factor in various cancers through neurotensin receptor 1, activating oncogenic pathways that support tumor growth, invasion, and survival." (PMID 41301028, 2025). "Neurotensin is known for its regulatory role in the nervous and gastrointestinal system, but its function extends to the modulation of cancer cell behavior." (PMID 39334861, 2024). "Neurotensin and Neuromedin N neuropeptides, will be further investigated as theranostic agents for cancers overexpressing neurotensin receptors." (PMID 38543026, 2024). "Radiolabeled neurotensin analogs have been developed as candidates for theranostic use against neurotensin subtype 1 receptor (NTS1R)-expressing cancer." (PMID 37958525, 2023). "Neuropeptides such as galanin (GAL), angiotensin II, apelin, adrenomedullin, endothelin-1, bombesin, orexin, substance P, neuropeptide Y, calcitonin gene-related peptide, vasoactive intestinal peptide and neurotensin are involved in cancer." (PMID 35954419, 2022). "This review is a comprehensive summary of the molecular pathways by which Neurotensin and its receptors act in cancer cells." (PMID 32336282, 2020). "Although some key genes were shared between models, such as Neurotensin and Galanin being upregulated in cancer induced bone pain and PSL neuropathic pain models, the majority of dysregulated genes were exclusive to each pain model." (PMID 30079380, 2018). "In previous studies we investigated the cancer selectivity of tetra-branched peptides containing the sequence of human neurotensin, which we named NT4." (PMID 29100299, 2017). "Neurotensin plasma values differentiate healthy people from patients suffering from colonic pathologies such as adenomatous polyps and cancer." (PMID 28560510, 2017). "Recent studies also showed that dysfunctional activation of the neurotensin/IL-8 pathway in HCC is associated with increased inflammatory response in the tumor microenvironment, enhanced EMT in cancer, and worse prognosis of HCC patients." (PMID 27117207, 2016). "Several reports indicate the high-affinity receptor of NT (neurotensin), NTR1 (neurotensin receptor 1), in numerous detrimental functions linked to neoplastic progression of several cancer types." (PMID 26215716, 2015). "Neurotensin deregulation has been observed in many cancers such as in colonic adenocarcinomas, small cell lung carcinomas, non-small cell lung adenocarcinomas, medullary thyroid carcinomas, and in fibrolamellar HCCs." (PMID 23335914, 2012). "Neurotensin has also been found to induce a proinflammatory tumour microenvironment and promote cancer cell invasion through pathways that involved NF-κB, PKC, ERK, and the sodium-proton exchanger 1 (NHE1)." (PMID 21961726, 2011). "Neurotensin (NT) is a peptide involved in digestion, neuromodulation, and cancer progression." (PMID 39519199, 2024).
cancer (continued). "Hence, they highlight the need for further validation of this promising concept in the field of neurotensin radioligands in cancer theranostics." (PMID 32526874, 2020). "It has been demonstrated that NT4 branched neurotensin peptides are much more selective than native monomeric neurotensin in binding to different human cancer cells and tissues and that conjugation to different functional units does not affect its binding properties." (PMID 25984525, 2015). "The expression of NTS and NTSR3 in cancer tissue had a positive correlation which was statistically significant (R = 0.46, p < 0.01)." (PMID 32764278, 2020). "Neurotensin and its receptors including NTSR2 play an important role in oncogenic progression of cancer malignancies." (PMID 28458684, 2017). "Although neurotensin has been previously shown to predict cardiometabolic disease and cancer, in this RCT study of overweight individuals, we paradoxically observed increased release of neurotensin during non-surgical weight-loss." (PMID 36316682, 2022). "One of the most studied neuropeptides involved in cancer progression is neurotensin (NTS), the three known receptors of which (two G-protein coupled receptors, NTSR1 and NTSR2, and a type I receptor, NTSR3) are expressed in numerous cancers and particularly in digestive cancers." (PMID 36233189, 2022). "In the top 50 differentially expressed genes between cancer and normal tissues, three genes: neurotensin (NTS, red arrow), keratin 19 (KRT19) and matrix metallopeptidase 12 (MMP12) were screened out for their high expression in 2 cancer samples (c-13426 and c-13732)." (PMID 23418512, 2013). "Besides, the clinical success for radiolabeled somatostatin analogs both with diagnostic and therapeutic radionuclides paved the way for new promising peptide derivatives, such as bombesin, neurotensin, or CXCR4 ligands, and, in a similar way, PSMA ligands, for cancer theranostics." (PMID 32887456, 2020). "In this study, we uncover a previously unknown mechanism by which TTK exerts a significant oncogenic effect by the upregulation of neurotensin (NTS) and dihydropyrimidinase-like 3 (DPYSL3), which promote cancer growth and cancer progression consequently tumor metastasis." (PMID 32121246, 2020). "Experiments using a specific antagonist or knockdown of the NTSR1 using short interfering RNA suggest that NTSR1 mediates the effects of neurotensin on cancer cells, although NTSR3/sortilin, which is often coexpressed in cancer cells, may modulate NTSR1 signalling." (PMID 21961726, 2011). "However, it must be noted that there is a plethora of evidence of expression of NTs and Trks in non-neuronal cells, although much of this is in the context of cancer." (PMID 23316162, 2012). "The cancer selectivity of NT4 peptides is much higher than that of native monomeric neurotensin, which unlike NT4 does not discriminate between healthy human tissues and cancer." (PMID 29100299, 2017).
tumor (42 papers, 2014 to 2026). "Regulatory peptides, such as neurotensin, are suitable agents for specific delivery of radioisotopes to tumour cells, for both diagnostic and therapeutic applications." (PMID 33917046, 2021). "The nTS+ group, characterized by rapid tumor growth and specific molecular markers, had limited access to curative treatments like RFA or transplantation." (PMID 39456643, 2024). "The proliferation of tumor cells can be induced by the binding of neurotensin to NTSR1 via several signalling pathways, including the phospholipase C pathway." (PMID 38496894, 2024). "Neurotensin stimulates the proliferation in vitro of tumour cell lines originating from the pancreas, prostate, astrocytes, and lung." (PMID 38543026, 2024). "For the management of tumours, neurotensin antagonists such as SR48692 have been developed." (PMID 38496894, 2024). "In particular, we discuss the effect of neurotensin, GDF-15, S1P (including the drug FTY720), and infection with CMV on tumor-associated macrophages (TAM), microglial cells, neutrophil and regulatory T cells (Treg), on the tumor microenvironment." (PMID 29467963, 2018). "Serum neurotensin, a new tumour marker for FHCC may discriminate it from HCC especially as a negative or normal value of alpha fetoprotein (AFP) tumour marker does not exclude an HCC." (PMID 30305894, 2018). "Neurotensin (NTS) is a peptide discovered in 1973, which has been studied in many fields and mainly in oncology for its action in tumor growth and proliferation." (PMID 36902025, 2023). "Oncolytic adenoviruses can be chemically conjugated with neurotensin-conjugated PEF to reduce immunogenicity and improve tumour selectivity through the neurotensin receptor." (PMID 37031291, 2023). "We show that neurotensin (NTS) and its high affinity receptor (NTSR1) contribute to the enhancement of experimental tumor growth and metastasis emergence in an experimental mice model." (PMID 25249538, 2014). "The authors discuss that neurotensin may be produced by the non-tumor cells in the tumor microenvironment and highlight that the contribution of the tumor microenvironment as a plausible source of neurotensin is still under extensive investigation." (PMID 33572108, 2021). "Serum neurotensin, a new tumour marker for FHCC may discriminate it from HCC especially as a negative or normal value of alpha feto-protein tumour marker does not exclude an HCC." (PMID 26342351, 2015).
psychiatric disorder (5 papers, 2013 to 2023). A disorder characterized by behavioral and/or psychological abnormalities, often accompanied by physical symptoms. "They analyzed preclinical and clinical evidence on nonpeptidergic ligands for neuropeptide receptors in psychiatric disorders mainly focusing on tachykinins, CRF, vasopressin, and neurotensin." (PMID 23986909, 2013).
infection (2 papers, 2018 to 2019). The state of being infected such as from the introduction of a foreign agent such as serum, vaccine, antigenic substance or organism. "This has resulted in significant progress over the last 4 years in the understanding of the previously little known secretory factors such as neurotensin (NT), growth differentiation factor-15 (GDF-15), sphingosine-1-phosphate S1P, and of infection with cytomegalovirus (CMV)." (PMID 29467963, 2018).
metabolic disease (2 papers, 2020 to 2022). A congenital disorder (due to inherited enzyme abnormality) or acquired (due to failure of a metabolically important organ) disorder resulting from an abnormal metabolic process. "Findings of this study can be of importance for future treatment strategies for metabolic diseases and CVD through neurotensin related mechanisms." (PMID 32825823, 2020).
NTS also shares sentences with these, for which no sentence is quoted: Hepatic steatosis (4 papers); cardiovascular disease (3); Parkinson disease (3); adenoma (1); adenomyosis (1); bipolar disorder (1); breast tumors (1); colorectal adenocarcinoma (1); Congestive Cardiac Failure (1); cytomegalovirus infection (1); essential hypertension (1); fibrolamellar hepatocellular carcinoma (1); hematological disease (1); Huntington disease (1); invasive breast carcinoma (1); liver cirrhosis (1); lung adenocarcinoma (1); malaria (1); malignant glioma (1); mental disorder (1); myocardial infarction (1); neurodegenerative disease (1); neurodevelopmental disorder (1); non-small cell lung carcinoma (1); ovarian carcinoma (1); pancreatic adenocarcinoma (1); Pancreatic endocrine tumors (1); Partington syndrome (1); Pfeiffer syndrome (1); prostate tumour (1).
A further 4 diseases each share a sentence with NTS in 1 paper.